IL18BP (interleukin 18 binding protein)
Diseases named in the same sentence as IL18BP in open-access papers (continued):
Sharing a sentence is not in itself a finding about the gene and the disease.
ovarian carcinoma (6 papers, 2014 to 2025). A malignant neoplasm originating from the surface ovarian epithelium. "The results also showed a significantly higher IL-18/IL-18BP ratio for ovarian cancer tissue and significantly higher IL-18BP expression in physiological ovarian tissue." (PMID 41561739, 2025). "We previously showed that IL-27, similar to IFN-γ, upregulated the expression of IL-18BP, a natural inhibitor of IL-18 activity, in ovarian cancer cells, and that IL-18BP protein accumulates in the ascites of patients." (PMID 28255204, 2017). "We reported that IL-27 induces the expression of the IL-18 inhibitor IL-18BP, in human Epithelial Ovarian Cancer (EOC) cells, thus potentially limiting the immune response." (PMID 26657115, 2015). "In our study, ovarian carcinoma patients with low IL18BP expression had poorer prognoses." (PMID 31257224, 2019). "We initially chose the SKOV3 ovarian cancer cell line, which has been widely utilized as a serous ovarian adenocarcinoma cell model, and responds to IL-27 stimulation by up-regulating the expression of immune regulatory IL-18BP, IDO, and PD-L1 molecules." (PMID 27683036, 2016). "However, our recent data showed that, beyond these anti-tumor effects, IL-27 also induces the expression of immune regulatory molecules such as IL-18BP, the natural inhibitor of the Th1-inducing cytokine IL-18, in ovarian cancer cells." (PMID 27683036, 2016). "Additionally, we emphasize the significance of IL-18BP regulation mechanism in ovarian carcinoma progression." (PMID 24963217, 2014). "Similarly, IL-27 was found to induce the expression of immune-regulatory molecules such as IL-18BP, the natural inhibitor of IL-18, and PD-L1 and IDO in human ovarian cancer cells and also in other cancer cells in vitro." (PMID 28255204, 2017).
psoriasis (6 papers, 2012 to 2024). An autoimmune condition characterized by red, well-delineated plaques with silvery scales that are usually on the extensor surfaces and scalp. "Furthermore, IL-18 and IL-18BP are also implicated in developing psoriasis, atopic dermatitis (AD), lupus erythematosus (LE), and other inflammatory skin diseases." (PMID 36742296, 2023). "This literature review will address the most recent updates regarding IL-18 and IL-18BP in psoriasis, atopic dermatitis, rosacea, and bullous pemphigoid and discuss the underlying impacts of IL-18 and IL-18BP and inflammatory disease in the skin." (PMID 36742296, 2023). "Of the 12 altered protein, 5 protein-disease causalities were supported by MR, i.e., LTA-celiac disease (PIVW = 1.29 × 10−3), IL18BP-Crohn’s disease (PIVW = 4.04 × 10−2), DDR1-Graves’ disease (PIVW = 3.37 × 10−3), CDSN-psoriasis (PIVW = 4.02 × 10−7), and BTN3A2-SD (PIVW = 3.93×10−5)." (PMID 39009607, 2024).
atherosclerosis (5 papers, 2015 to 2025). A disease characterized by the build-up of fatty material and calcium deposition in the arterial wall resulting in partial or complete occlusion of the arterial lumen. "Intriguingly, among these secreted proteins, PLTP, CD5L, and LPL have been reported to exacerbate or be associated with advanced atherosclerosis, whereas IL18BP is anti‐atherogenic." (PMID 33231376, 2021). "In murine models of atherosclerosis, IL-18BP reduces fatty streak development, and slows progression of advanced atherosclerotic plaques in the thoracic aorta of apoE knockout mice." (PMID 25699211, 2015).
COVID-19 (5 papers, 2020 to 2024). A disease caused by infection with severe acute respiratory syndrome coronavirus 2. "A study performed on two cohorts of severely ill patients in two hospitals in Washington identified IL-18BP as one of three biomarkers for COVID-19-associated secondary HLH." (PMID 39769266, 2024). "In this study, levels of IL-1β, IL-1RA, IL-18, and IL-18BP were higher in patients with COVID-19 than in HVs; however, they were lower than in patients with canonical autoinflammatory diseases." (PMID 33232303, 2021). "The level of IL-18BP is not usually detected in COVID-19, thus a comparison of IL-18 binding protein (IL-18BP) level is not performed in our study." (PMID 33552062, 2020).
Hepatitis (5 papers, 2013 to 2025). Inflammation of the liver. "In line with this fact, the loss of IL-18BP function seems to be fatal for humans, considering that in 2019 a case report confirmed the death of a child with a loss-of-function mutation in IL-18BP (homozygous 40-nucleotide deletion) upon hepatitis A virus infection." (PMID 35885055, 2022). "Several host genetic factors have been shown to be linked to the severity of hepatitis A. A patient with fulminant hepatitis presented with a 40 nt homozygous deletion in the IL-18 binding protein (IL-18BP) gene generating three novel splice variants of IL-18BP." (PMID 34066709, 2021). "We report a second family with FVH triggered by HAV in two children and self-healing hepatitis triggered by CMV/EBV in a third child from the same family, due to preexisting, inherited complete IL-18BP deficiency." (PMID 41334112, 2025). "Overall, both IL-18BP and TIM-1 genes are biologically plausible susceptibility genes for hepatitis A, facilitating a risk evaluation for developing severe viral hepatitis in patients." (PMID 34066709, 2021). "Our results strongly suggest that IL-18BP/IL-4 gene transfer can prevent ConA-mediated hepatitis and liver injury." (PMID 23516562, 2013). "Our data show for the first time the marked effect of modifying Th1/Th2 imbalance in ConA-induced hepatitis mice after local Ad-IL-18BP/IL-4 gene therapy." (PMID 23516562, 2013). "We also found that serum levels of IL-18 were significantly downregulated in response to local Ad-IL-18BP/IL-4 treatment in mice with hepatitis." (PMID 23516562, 2013). "The therapeutic use of IL-18BP might therefore modulate the cytokine balance, ameliorating established hepatitis." (PMID 23516562, 2013). "We found that Ad-IL-18BP/IL-4 treatment resulted in marked attenuation of Akt, p38 MAPK, NF-κB p65 and JNK1-2 activity in ConA-induced hepatitis." (PMID 23516562, 2013). "Interestingly, while the Algerian and two Egyptian siblings died of HAV FVH, the third Egyptian child recovered from hepatitis triggered by CMV and EBV, implying that IL-18BP is more important for the control of HAV than for the control of herpes viruses." (PMID 41334112, 2025).
Wegener’s granulomatosis (5 papers, 2010 to 2024). "Patients with Wegener’s granulomatosis have high serum levels of both IL-18 and IL-18BP." (PMID 38727246, 2024).
Obesity (4 papers, 2021 to 2026). Accumulation of substantial excess body fat. "In addition, more pre-clinical studies involving IL-18 regulatory steps, such as maturation by inflammasome, retention by IL-18BP or antagonism by anti-IL-18 or anti-IL-18R antibodies could open new therapeutic options for patients with metabolic diseases such as obesity, diabetes, and NAFLD/NASH." (PMID 36313762, 2022). "Circulating levels of the intestinal inflammatory factors CCL5 and IL-6 as well as the IL-18/IL-18BP ratio were increased (P < 0.05) in patients with obesity with and without T2D being also significantly associated with endotoxin levels." (PMID 38315242, 2024).
osteoporosis (4 papers, 2016 to 2023). A condition of reduced bone mass, with decreased cortical thickness and a decrease in the number and size of the trabeculae of cancellous bone (but normal chemical composition), resulting in increased fracture incidence. "IL-18-binding protein (IL-18BP) is an antagonist of IL-18, and high serum IL-18BP is associated with a low risk of osteoporosis in postmenopausal women." (PMID 35628185, 2022). "The treatment of OVX mice with IL-18BP prevented bone loss, and in women with osteoporosis, IL-18BP levels decreased while serum IL-18 levels increased, suggesting that IL-18BP may be used to treat postmenopausal osteoporosis." (PMID 37475866, 2023). "Thus high serum IL-18BP levels are associated with lower risk of osteoporosis in postmenopausal women." (PMID 27649785, 2016). "In one study, IL-18BP was decreased in female patients with osteoporosis, and IL-18BP treatment showed anti-osteoporotic effects in an osteoporosis mouse model." (PMID 34530864, 2021).
Sepsis (4 papers, 2016 to 2024). Sepsis is defined as life-threatening organ dysfunction caused by a dysregulated host response to infection. "Other transcripts upregulated in CD5L− peritoneal cells, including Osm, Il18bp, Ripk1, Nub1, Tlr2, Stat1, Irf1, Nfkb1, Pik3r5, or their coding proteins, were already associated with sepsis severity." (PMID 38750020, 2024). "Serum inflammatory mediators associated with sepsis (IL-18, IL-18BP, TNF) were determined and correlated with the outcome of SBT." (PMID 35054259, 2021).
viral infection (4 papers, 2014 to 2025). "In human patients, it has been reported that rare genetic loss-of-function of IL-18BP results in fulminant hepatitis following a viral infection." (PMID 41275524, 2025). "IL18BP may be a determinant of immune response to viral infections including hepatitis C, and bacterial infections such as brucellosis; however, no prior studies have examined IL-18BP in the context of dengue and leptospirosis." (PMID 24444080, 2014).
Arthritis (3 papers, 2013 to 2023). Inflammation of a joint. "As a consequence of their lack of stimulatory effects on immune cells, we have utilized the gene transfer of adenoviral vectors encoding IL-18BP and IL-4 in previous experiments, and shown this to be effective in animal models of immune inflammatory diseases, such as arthritis." (PMID 23516562, 2013). "The incidence and severity of arthritis, including mRNA levels of different cytokines, were compared in IL-18BP or IL-18 knock-out (KO) mice and their WT littermates." (PMID 37415987, 2023). "Since both sJIA and AOSD are characterized by dysregulated innate immune responses, we decided to investigate the role of the IL-18/IL-18BP balance in an experimental model of arthritis that is uniquely dependent on innate immune responses." (PMID 37415987, 2023). "To further assess the severity of arthritis, we measured the mRNA levels of a variety of pro-inflammatory cytokines and chemokines, including Il18bp, Il18, Il1b, Il6, Il1r2, Ifng, Cxcl9, Cxcl1, and Cxcl2 in arthritic joints of IL-18BP KO and WT littermates." (PMID 37415987, 2023). "The incidence and severity of arthritis were similar in IL-18BP KO and IL-18 KO compared to their WT littermates." (PMID 37415987, 2023). "This study examines the expression and function of IL-18 and IL-18BP in K/BxN serum transfer arthritis (STA), a model that is uniquely dependent on innate immune responses." (PMID 37415987, 2023). "Administration of mouse IL-18BP as a fusion protein with the Fc portion of murine IgG1 significantly attenuated the clinical and histological scores of arthritis as compared to PBS-treated mice." (PMID 37415987, 2023). "In the collagen-induced arthritis model, overexpression or administration of IL-18BP reduced the severity of arthritis." (PMID 34530864, 2021). "Moreover, local overexpression of IL-18BP by adenoviral delivery has been shown to ameliorate tissue destruction in a model of arthritis." (PMID 23516562, 2013). "Indeed, arthritis severity was markedly attenuated in IL-18 knock-out (KO) mice, as well as by the administration of neutralizing anti-IL-18 antibodies and recombinant human IL-18BP." (PMID 37415987, 2023). "Naïve and serum transfer-induced arthritis (STA) wild-type (WT) mice were used to examine the articular levels of IL-18 and IL-18BP mRNA by RT-qPCR." (PMID 37415987, 2023). "Using IL-18BP and IL-18 KO mice, we showed that neither IL-18 nor IL-18BP was required to control the incidence and severity of arthritis." (PMID 37415987, 2023).
breast carcinoma (3 papers, 2017 to 2022). "The predicted putative marker proteins EDEM2 and IL18BP are especially interesting, because their genes were found to be significantly upregulated in all breast cancer microarrays included in the analysis." (PMID 36140706, 2022). "Our results revealed increased levels of both IL-18 and IL-18BP in breast cancer whereas in dense breast tissue IL-18 alone was increased." (PMID 29387062, 2017). "Increased levels of IL-18 were found in dense breast tissue as well as in breast cancer, but IL-18BP was increased in breast cancer only." (PMID 29387062, 2017). "Interleukin-18-binding protein (IL18BP) regulates the activity of IL-18, which has been shown to be higher in breast carcinoma tissue compared to tissue from patients with benign breast disease." (PMID 28391240, 2017). "CCL-19 and -24, CXCL-1 and -10, and IL-6 were increased in dense breast tissue only, whereas IL-18BP was increased in breast cancer only." (PMID 29387062, 2017).
chronic kidney disease (3 papers, 2015 to 2024). Impairment of the renal function secondary to chronic kidney damage persisting for three or more months. "Interleukin-18 binding protein is a natural inhibitor of IL-18, which is involved in immunosuppression in chronic kidney disease through the reduction of excretion." (PMID 26496326, 2015). "In addition, there is also an increase in the plasma IL-18BP levels in many human diseases, including acute and chronic renal failure; however, the levels of IL-18BP secretion in LN require further analysis." (PMID 35054831, 2022).
Crohn disease (3 papers, 2020 to 2026). A gastrointestinal disorder characterized by chronic inflammation involving all layers of the intestinal wall, noncaseating granulomas affecting the intestinal wall and regional lymph nodes, and transmural fibrosis. "Phase II clinical trials of IL-18BP are underway in renal transplantation, Crohn’s disease and Behcet’s disease." (PMID 41592067, 2026). "For example, significantly increased expression of LTA (P = 2.20 × 10−16) in celiac disease, IL18BP (P = 3.28 × 10−10) in Crohn’s disease, and DDR1 (P = 2.20 × 10−16) in Graves’ disease were observed." (PMID 39009607, 2024).
dengue (3 papers, 2014 to 2022). "Information derived from circulating levels of novel biomarkers improved diagnostic accuracy, with sEng and IL18BP showing the best performance individually and in multivariable models to distinguish between dengue and leptospirosis." (PMID 24444080, 2014). "Host biomarkers sEng and IL-18BP compare favourably with another recently commercialized point-of-care diagnostic modality for dengue based on detection of the virus NS1 antigen." (PMID 24444080, 2014). "In our study, the sensitivity and specificity of elevated sEng for the diagnosis of dengue (relative to patients with leptospirosis) were 80% and 94%, and for IL-18BP were 95% and 83%, respectively, using optimal thresholds for the study population." (PMID 24444080, 2014). "Our work examined a broad and diverse panel of host proteins, demonstrating that sEng and IL18BP in particular were differentially upregulated in dengue relative to leptospirosis and healthy controls." (PMID 24444080, 2014). "In our cohort, nearly all dengue patients and approximately half of leptospirosis patients had elevated levels of IL-18BP relative to healthy norms and IL-18BP was further elevated in dengue compared to leptospirosis." (PMID 24444080, 2014). "This suggests that the cytokine storm occurring in severe dengue disease may be due to inadequate regulation of IL-18 responses by IL-18BP." (PMID 35874775, 2022). "Hence, the use IL-18BP appears to serve as a promising therapeutic strategy against severe dengue disease warranting investigations." (PMID 35874775, 2022). "Having showed that plasma levels of IL-18 was associated with the severity of dengue disease, we next assessed the circulating levels of this regulatory molecule and the free circulating IL-18 (fraction of IL-18 that do not bound to IL-18BP)." (PMID 28569153, 2017). "Elevated levels of IL-18 and IL-18BP have been observed in patients with idiopathic thrombocytopenia purpura, suggesting a possible link to reduced platelet number and/or function, as in severe dengue and leptospirosis." (PMID 24444080, 2014). "Quantitative IL-18BP levels were higher in dengue than leptospirosis and could accurately be used to differentiate the two infections, both as an individual quantitative biomarker and in combination with other clinical and biochemical features." (PMID 24444080, 2014). "Median levels of Angptl3, IL-18BP, CXCL10, Platelet Factor 4, sICAM-1, Factor D, sEng and sKDR were higher in dengue fever compared to leptospirosis (p < 0.001 for all)." (PMID 24444080, 2014). "There were five biomarkers where the median levels were outside the population-derived normal range in dengue fever, but not leptospirosis: Angptl3, IL-18BP, CXCL10, sICAM-1, and sEng." (PMID 24444080, 2014). "Nine biomarkers differed significantly between dengue fever and leptospirosis, with higher levels of Angptl3, IL-18BP, IP-10/CXCL10, Platelet Factor 4, sICAM-1, Factor D, sEng and sKDR in dengue and higher levels of sTie-2 in leptospirosis (p < 0.001 for all comparisons)." (PMID 24444080, 2014). "Elevated levels of sEng and IL18BP point strongly to a diagnosis of dengue virus infection, rather than leptospirosis." (PMID 24444080, 2014).
Fulminant hepatitis (3 papers, 2021 to 2025). Acute hepatitis complicated by acute liver failure with hepatic encephalopathy occurring less than 8 weeks after the onset of jaundice. "Intriguingly, one report demonstrates a protective role of intrahepatic IL-18BP for liver-specific inflammation in a patient carrying homozygous loss-of-function mutation in IL-18BP who succumbed to fulminant hepatitis due to hepatitis A virus." (PMID 35958573, 2022).
keloid (3 papers, 2021 to 2025). An irregularly shaped, elevated mark on the skin caused by deposits of excessive amounts of collagen during wound healing. "Fibroblasts derived from patients with keloids had increased IL-18 levels, while IL-18BP levels remained the same." (PMID 35625564, 2022). "Studies of the expression of IL-18 and IL-18BP in keloid keratinocyte/keloid fibroblast cocultures showed a significant elevation of bioactive IL-18 whereas IL-18BP levels remained the same." (PMID 35625564, 2022). "Studies on the expression of IL-18 and its antagonist, IL-18 Binding Protein (IL-18BP), using a coculture model demonstrated severe IL-18⁄IL-18BP imbalance in keloid keratinocyte/keloid fibroblast cocultures with significant elevation of bioactive IL-18 whereas IL-18BP levels remained the same." (PMID 39799030, 2025). "Moreover, when keratinocytes and keloid fibroblasts (KK/KF) were cocultured, IL-18/IL-18BP was seriously unbalanced, which promoted the formation of keloid." (PMID 33959031, 2021).